IL1B (interleukin 1 beta)
Diseases named in the same sentence as IL1B in open-access papers (continued):
Sharing a sentence is not in itself a finding about the gene and the disease.
injury (continued). "In addition, H2S significantly suppressed NLRP3 inflammasome activation and subsequent IL-1β excretion in PQ-induced acute liver injury." (PMID 32064027, 2020). "Notably, caspase-1, IL-1β, and IL-18, the well-known markers of pyroptosis, which have been shown to be increased in other disease states such as lung injury, kidney inflammation, cardiomyopathy, and liver damage, were increased after Dox treatment." (PMID 33316945, 2020). "However, the secretion of IL-1β by KCs is one of the upstream events in Con A-induced liver injury, and CyA can inhibit the secretion of IL-1β." (PMID 30893870, 2019). "IL-1β inhibits fluid transport across the distal lung epithelium, resulting in surfactant abnormalities and increased protein permeability across the alveolar-capillary barrier, playing a key role in the development of acute PQ-induced lung injury." (PMID 29566055, 2018). "TNF-α and IL-1β are mainly from monocytes and macrophages in the acute and chronic liver injury and may trigger the production of many other proinflammatory cytokines and induce hepatocyte death through the recruitment of neutrophils." (PMID 29743924, 2018). "The present study employs an interleukin-1β (IL-1β) stimulated primary cortical astrocyte model in vitro and a nigrostriatal pathway injury model in vivo to mimic the astrocyte activation induced by traumatic brain injury." (PMID 28356158, 2017). "Furthermore a downregulation of Nlrp1 inflammasome, which is necessary for IL-1β synthesis, has been described in trauma patients." (PMID 28255201, 2017). "We also found that OMT could suppress the synthesis of tumor necrosis factor –alpha (TNF-α), interleukin-1beta (IL-1β) and interleukin-6 (IL-6) after traumatic brain injury via NF-κB pathway." (PMID 24250585, 2013). "In the present study, we provide the first evidence that in the DRG, PAFR is important in the pathogenesis of tactile allodynia, a major behavioral consequence of nerve injury, and are responsible for production of proinflammatory cytokines such as TNFα and IL-1β." (PMID 20454616, 2010). "In addition, IL-1β, IL-6, TNFα, and the chemokines CCL5 and CXCL2 (which were all upregulated by LPA in primary microglia) are implicated as modulators of the neuroinflammatory response during traumatic brain injury where LPA levels are increased." (PMID 27565558, 2016). "IL-1β may be a potential target in the management of neuropathic pain after nerve injury." (PMID 24009718, 2013). "In response to hypoxic kidney injury, PTEC-derived danger signals selectively trigger the release of IL-1β by activated myeloid cells (e.g., macrophages, DCs)." (PMID 39890773, 2025). "D-gal induction led to upregulated mRNA expression of pro-inflammatory cytokines (IL-6, IL-1β, and TNF-α), which are core drivers of the inflammatory cascade in persistent liver injury." (PMID 41614837, 2025). "Liu and collaborators showed that 4-HPA was able to reduce the levels of the pro-inflammatory cytokines TNF-α, IL-1β, IL-6, and HIF-1α and prevent lung oedema in a rat model of acute lung injury." (PMID 39000542, 2024). "LPS-induced acute liver injury occurs due to inflammatory mediators such as TNF-α, IL-1β, and ROS, affecting mitochondrial function and hepatocyte apoptosis, affecting Kupffer cells and hepatocytes." (PMID 39101083, 2024). "In the CCl4-induced liver injury mice model, the effect of Sal B and 2-DG on plasma lactate was examined, while the expression of Pan Kla, LDHA, NLRP3, and IL-1β proteins was also detected and quantitatively analyzed by immunohistochemistry." (PMID 38202819, 2024). "An integrative review of 37 studies identified an elevation of IL-6, IL-1β, IL-8 and TNF-α during the first 3 weeks of life as potential, independent predictors of brain injury and neurodevelopmental impairment." (PMID 37049507, 2023).
injury (continued). "On the contrary, using two different models of perinatal brain injury, CGS21680 produced a partial increase of some microglial cytokines such as IL-1β and TNF-α, as well as an increase of iNOS." (PMID 35387355, 2022). "In this study, the levels of the pro-inflammatory markers (IL-6, IL-1β, TNF-α, and NF-kB) were high in the pulmonary tissues of the BLM-induced model of acute lung injury." (PMID 36500388, 2022). "In our study, the concentrations of these pro-inflammatory biomarkers (TNF-α, IL-6, IL-1β, and NF-κB) were markedly elevated in lung tissue homogenate of the BLM mice model of acute lung injury." (PMID 35808662, 2022). "They found that the expression levels of p38 MAPK, NF-κB p65, IL-1β, and TNF-α protein in rats with kidney injury were significantly higher than those in the control group." (PMID 36296715, 2022). "PF reduced BUN, Scr, and IL-1β levels and attenuated inflammatory responses by inhibiting CXCR3/CXCL activation in mice with concanavalin A (ConA)-induced renal injury." (PMID 34437444, 2021). "Our results showed that CD significantly reduced synthesis of TNF-α, IL-1β, and IL-6 in serum, indicating that CD treatment alleviated the inflammatory responses due to APAP-induced liver injury." (PMID 33364966, 2020). "When myocardial ischemia-reperfusion injury occurs, the expression of pro-inflammatory factors increased, mainly due to the increased release of TNF-α and IL-1β." (PMID 32116705, 2020). "HMGB1 has also been shown to drive the alveolar macrophage production of inflammatory factors, including IL-1β and TNF-α, thereby inducing acute lung injury." (PMID 31958320, 2020). "However, excessive and prolonged training with insufficient recovery might cause musculoskeletal trauma with increased production of proinflammatory cytokines such as TNF- α, IL-1β, and IL-6, which contributes to symptoms related to performance decrement and exercise-induced fatigue." (PMID 32082125, 2019). "The results also showed that white tea downregulated the expression of COX-2, iNOS, NF-κB, IL-1β, and TNF-α in mice with liver injury and upregulated the expression of IκB-α, thus alleviating liver injury by inhibiting oxidative stress." (PMID 30875793, 2019). "TNF-α and IL-1β, two major proinflammatory cytokines, play a major role in exacerbating ICH-induced brain injury." (PMID 30498516, 2018). "Taken together, both studies indicate that the expression of IL-1β, TNF-α, IL-8, and MCP-1 can be upregulated in acute lung injury in both mice and guinea pigs." (PMID 27446082, 2016). "Previous reports showed that M1 monocytes activated by brain inflammation or brain injury secrete the pro-inflammatory cytokines TNF-α and IL-1β." (PMID 24303068, 2013). "BAL levels of CXCL1, CXCL2, IL-1β, TNFα and TGFβ were increased during the early phase, while IGF-1 levels were significantly increased in the later phase, suggesting that IGF-1 is involved in the resolution processes of acute lung injury." (PMID 41431237, 2026). "In addition, protocatechuic acid demonstrated protection against the development of LPS-induced acute lung injury in mice by lowering the levels of TNF-α and IL-1β." (PMID 39129025, 2024). "Aerobic exercise can also modulate the inflammatory/anti-inflammatory and oxidative/antioxidative balance in the early stage of LPS-induced lung injury, which leads to a decrease in the release of inflammatory mediators such as TNF-α, IL-6, IL-10, IL-1β, IL-17, GM-CSF, and CXCL1/KC." (PMID 36456896, 2022). "On the other hand, another study reported that epigallocatechin gallate (EGCG) could attenuate lipopolysaccharide-stimulated acute lung injury in mice and restrained the liberation of inflammatory cytokines TNF-α, IL-1β, and IL-6." (PMID 36290242, 2022).
injury (continued). "Therefore, excessive pro-inflammatory cytokines, such as IL-1β, IL-6, and TNFα, are considered to be the precursors of APAP-induced liver injury, and these pro-inflammatory cytokines are considered to affect the process of APAP-induced liver injury." (PMID 34639126, 2021). "The earlier studies showed M1 inflammatory mediators like iNOS, Il-1β, IL-6 etc. are the key players to initiate inflammatory processes and ALI and modulation of the M1 inflammatory marker were beneficial for the resolution of acute lung injury." (PMID 32575718, 2020). "An animal experiment found that HS may ameliorate the brain edema and brain injury induced by traumatic brain injury by reducing TNF‐ɑ‐ and IL‐1β‐mediated pro‐inflammatory activation." (PMID 32529750, 2020). "NF-κB activation during the process of alcohol-mediated liver injury might be caused by drug-metabolizing enzyme-induced oxidative stress, whereas IL-1β, TNF-α, and iNOS might be the primary NF-κB-inducing factors during immune-mediated liver injury." (PMID 31881060, 2019). "Similarly, we also found that, compared to sham rats, IL-1β, CXCL1, CXCL11, CCL2, and transcription factor (Spil/Pu.1, Runx3, and IκBz) are obviously elevated at 7 days following nerve injury." (PMID 31708740, 2019). "However, the levels of hepatic TNF-α, IL-1β, IL-4, IL-6, and TGF-β1 were significantly lower in rats with 2-AAF/PH-induced liver injury treated with Pue and RAPA than in untreated rats with liver injury, and IL-10 expression was higher." (PMID 30405406, 2018). "The present results exhibited that LPS induced inflammation and immune suppression in the lung via influencing IgM, IgG, IL-1β, IL-6, and TNF-α, while indirubin markedly reduced IgM abundances and IL-1β and TNF-α mRNA abundances in LPS-induced acute lung injury." (PMID 28525368, 2017). "In sharp contrast to the steep increase in hepatic expression of IL-1β, IL-6, TNF-α and MMP-13 in the context of fulminant liver injury induced by D-GalN/LPS, the fibrotic mice were highly resistant to this attack, showing significantly less induction of inflammatory cytokines and MMP." (PMID 28874845, 2017). "The plasminogen activator urokinase receptor, which was found to be significantly increased 1–3 h after trauma, has been described to be upregulated by IL-1β and TNF-α, both of which have been reported to be increased early following clinical and experimental blunt chest trauma." (PMID 26303896, 2015). "Importantly, EPO administration 1 hour after injury was sufficient to reduce IL-1β to sham levels, highlighting EPO’s ability to modulate neuroinflammation early and robustly after diffuse TBI, as reported in models of focal brain injury." (PMID 24344874, 2013). "Targeting inflammatory pathways through IL-1β and TNF-α inhibitors has shown promise in reducing cardiovascular complications, and further exploration of immunomodulatory therapies may provide additional benefits in trauma-related myocardial dysfunction." (PMID 40710793, 2025). "In our study, IL-1β was significantly increased in the unfavorable patient group, highlighting its important role in neuroinflammatory processes and its prognostic value after acute brain injury, and interestingly irrespective of the type of brain injury." (PMID 39540961, 2024). "Results of the present study were similar to our prior study, which showed that LPS-induced acute lung injury mice administered Sanghuangporus sanghuang mycelium could significantly decrease concentrations of TNF-α, IL-1β, IL-6, and NO in bronchoalveolar lavage." (PMID 35111796, 2021). "The inhibition of TNF-α, IL-1β, and IL-6 production by AVA might occur through pathways that converge on NF-κB activation because they can regulate cytokine production in LPS-induced acute lung injury." (PMID 29483931, 2018). "Therefore, no obvious interaction exists between MMP-9 and IL-1β following disruption of BBB secondary to brain trauma/stress." (PMID 27795859, 2016).
injury (continued). "The results showed that Emo could not reduce the pulmonary inflammatory infiltration and lung injury score in the rat model of acute lung injury with granulocyte deficiency, nor could it reduce the levels of inflammatory factors TNF-α and IL-1β in lung homogenate." (PMID 32782444, 2020). "Our data did not directly address whether IL-1β mediates NRG1 release, as has been shown with bleomycin-induced lung injury." (PMID 30813222, 2019).
metabolic syndrome (180 papers, 2009 to 2026). A cluster of metabolic risk factors for CARDIOVASCULAR DISEASES and TYPE 2 DIABETES MELLITUS. "Metabolic syndrome associated inflammatory markers such as, IL-1β, MCP-1, TLR-4 and TNF-α were quantified in dietary lipid supplemented healthy and diabetic groups." (PMID 38755663, 2024). "We have demonstrated that inflammatory cytokines such as TNF-α, IL-6, and IL-1β are soluble mediators linked with ventricular arrhythmias and contractile dysfunction in a rat model of metabolic syndrome." (PMID 37661270, 2023). "High body mass index (BMI) was associated with lower levels of IL-1β, and metabolic syndrome with lower levels of IFN-γ after LPS stimulation." (PMID 36426370, 2022). "The increased levels of proinflammatory cytokines (TNF-α, IL-6, and IL-1β) have been found to be important contributors to the underlying processes of the development of metabolic syndrome." (PMID 30863477, 2019). "Both IL-1α and IL-1β gene polymorphisms have been reported to be associated with central obesity and metabolic syndrome in a population with coronary heart disease in an epidemiologic study." (PMID 31182982, 2019). "In this work, HDL reduction was also shown to induce higher IL-1β production in LPS-stimulated primary human monocytes and associate with increased IL-1β serum levels in patients with metabolic syndrome." (PMID 29850624, 2018). "However, we observed significant differences in parameters related to carbohydrate and lipid metabolism—key components associated with the risk of metabolic syndrome—as well as in the concentrations of proinflammatory markers, including IL-1β, IL-6, and CRP." (PMID 40944273, 2025). "We thus hypothesized that increased levels of FGF21 observed in patients with the metabolic syndrome are caused by an enhanced activity of inflammatory cytokines such as IL-1β." (PMID 33846498, 2021). "This condition is characterized by overproduction of proinflammatory mediators, such as circulating levels of C-reactive protein (CRP), TNF-α, and IL-1β, as well as insulin resistance and dyslipidemia, all of which are risk factors for cardiovascular diseases, metabolic syndrome, and diabetes." (PMID 26490535, 2015). "Increased IL-1β is recognized as a risk factor for the metabolic syndrome." (PMID 21274430, 2010). "In our study, IL-1β and IL-6 values also tended to be higher than in controls, and this confirms that survivors of childhood brain cancer may have a chronic inflammatory state that favors the onset of metabolic syndrome and cardiovascular risk." (PMID 38254811, 2024). "Attenuation of pro-inflammatory cytokines such as IL-6, TNFα, and IL-1β secreted by immune cells and adipocytes may be a therapeutic approach for treating systemic low-grade chronic inflammation-associated with metabolic syndrome." (PMID 29592806, 2018). "Multiple preclinical studies demonstrate that kefir administration reduces pro-inflammatory cytokine levels, including TNF-α, IL-1β, and IL-6, in rodent models of metabolic syndrome." (PMID 40565686, 2025). "Osali and Rostami further examined the impact of a 6-week moderate aerobic training program with nano-curcumin on pro-inflammatory cytokines (IL-1β, NO) and depressive symptoms in women with metabolic syndrome in the same age group." (PMID 41228407, 2025). "In both obese murine models and human liver tissues, enhanced expression of NLRP3 inflammasome components, increased CASPASE‐1 activity, and elevated levels of IL‐1β have been observed, correlating directly with the severity of metabolic syndrome phenotypes." (PMID 41169786, 2025). "Both population studies found that exposure to SO42− affected levels of IL-1β, IL-5, IL-7, IL-12, and IFN-γ, increasing the risk of metabolic syndrome, suggesting that SO42− affects systemic inflammation and metabolic disease." (PMID 39195631, 2024).
metabolic syndrome (continued). "Previous results from our research group demonstrated, in the genetic model of metabolic syndrome (Zucker rat), that increased NA has an inhibitory role in the release of IL-1β and stimulates the release of IL-6 by peritoneal macrophages." (PMID 39064652, 2024). "T2DM and metabolic syndrome are associated with a chronic state of low-grade inflammation, with increased serum levels of CRP and pro-inflammatory cytokines, such as IL-6, IL-1β and TNF-α." (PMID 38140319, 2023). "Bariatric surgery to obtain weight reduction in obese patients with CKD resulted, besides the improvement of all metabolic syndrome components, in a decrease of proteinuria and a correlated decrease in serum IL-1β concentrations." (PMID 35204131, 2022). "The DRS designed to model diabetic hyperglycemia and dyslipidemia were either ineffective or far less effective in eliciting significant alterations than TNFα or IL-1β." (PMID 35902594, 2022). "In conclusion, our study provides important new tools and insights for investigating the role of Il-1β and Il1r1 in a broad spectrum of diseases, such as autoinflammatory diseases, metabolic syndromes, acute and chronic inflammation, and malignancies." (PMID 36389773, 2022). "OPG level positively correlates with CRP in adult patients with metabolic syndrome, and TNFα together with IL-1β stimulated production of OPG by human retinal microvascular endothelial cells." (PMID 33604725, 2021). "Inflammatory cytokines such as TNF-α, IL-6, and IL-1β play significant roles in the etiology of metabolic syndrome." (PMID 34938803, 2021). "Kermani and coworkers demonstrated that C. sativus (100 mg/day) reduces VEGF, IL-2, and IL-1β while enhancing IL-10 levels compared to the placebo group in metabolic syndrome patients." (PMID 34956439, 2021). "As a consequence, we postulated that antagonism of the IL-1β inflammatory pathway would lower FGF21 levels in patients with the metabolic syndrome." (PMID 33846498, 2021). "Metaflammation in adipose tissue, characterized by infiltration of macrophages, local gene expression and secretion of pro-inflammatory factors, especially IL-6 and IL-1β, is considered a potential factor contributing to development of the metabolic syndrome." (PMID 30697360, 2019). "Horses with metabolic syndrome showed marked adipocyte hypertrophy and increased expression of adipokines (leptin) and inflammatory cytokines (TNFα,IL1β and CCL2) in both adipose tissue depots compared to healthy horses." (PMID 30866087, 2019). "On the opposite, the serum levels of IL-1β showed a significant 1.5-fold increase when studied in metabolic syndrome patients with low HDL levels as compared to metabolic syndrome patients without showing HDL reduction." (PMID 29850624, 2018). "In other words, culture conditions mimicking the levels of HDL that are found in metabolic syndrome do not only increase the NCM percentage but also enhance production of IL-1β." (PMID 29850624, 2018). "These in vitro findings agree with our in vivo results showing that serum values of IL-1β significantly increased in metabolic syndrome patients with low HDL levels as compared to metabolic syndrome patients without HDL reduction." (PMID 29850624, 2018). "Concurring with in vitro results, IL-1β serum values significantly increased in metabolic syndrome patients with low HDL levels as compared to metabolic syndrome patients without HDL reduction." (PMID 29850624, 2018). "Altogether, this information concurs with our data that demonstrate elevation in the serum levels of IL-1β in patients with metabolic syndrome." (PMID 29850624, 2018). "Abdominally obese patients with metabolic syndrome showed similar IL-1β serum levels than those found in metabolic syndrome patients without central obesity." (PMID 29850624, 2018). "Since not only monocyte subpopulations were modified by HDL but also their ability to produce IL-1β, we decided to measure IL-1β serum levels in the metabolic syndrome population." (PMID 29850624, 2018).